MIR3648-1 (microRNA 3648-1)
Synonyms: hsa-mir-3648; MIR3648; hsa-mir-3648-1
Gene: MicroRNA gene on chromosome 21 (8,208,473 to 8,208,652, forward strand). Ensembl gene ENSG00000275708.
Gene Ontology:
Biological process: positive regulation of osteoblast differentiation
Homologues: Paralogues in human: MIR3648-2 (100% identical).
Diseases named in the same sentence as MIR3648-1 in open-access papers:
MIR3648-1 is named in the same sentence as 4 diseases in open-access papers, as found by Europe PMC text mining. Sharing a sentence is not in itself a finding about the gene and the disease.
MIR3648-1 shares sentences with these, for which no sentence is quoted: cancer (1 paper); colon adenocarcinoma (1); colon adenoma (1); tumor (1).